RAB7B (RAB7B, member RAS oncogene family)
Description:
Controls vesicular trafficking from endosomes to the trans-Golgi network (TGN). Acts as a negative regulator of TLR9 signaling and can suppress TLR9-triggered TNFA, IL6, and IFNB production in macrophages by promoting TLR9 lysosomal degradation. Also negatively regulates TLR4 signaling in macrophages by promoting lysosomal degradation of TLR4. Promotes megakaryocytic differentiation by increasing NF-kappa-B-dependent IL6 production and subsequently enhancing the association of STAT3 with GATA1. Not involved in the regulation of the EGF- and EGFR degradation pathway.
Synonyms: MGC9726; MGC16212; RAB7
Tractability: PROTAC: its protein half-life has been measured.
Gene: Protein-coding gene on chromosome 1 (205,976,740 to 206,003,461, reverse strand). Ensembl gene ENSG00000276600.
Subcellular location: Late endosome; Lysosome; Golgi apparatus; Golgi apparatus, trans-Golgi network; Cytoplasmic vesicle, phagosome; Cytoplasmic vesicle, phagosome membrane
Pathways (Reactome):
Vesicle-mediated transport: RAB GEFs exchange GTP for GDP on RABs; TBC/RABGAPs
Metabolism of proteins: RAB geranylgeranylation
Gene Ontology:
Molecular function: G protein activity; protein binding; GTP binding; GTPase activity
Biological process: late endosome to Golgi transport; positive regulation of interleukin-6 production; positive regulation of megakaryocyte differentiation; endosome to lysosome transport; negative regulation of toll-like receptor 4 signaling pathway; negative regulation of toll-like receptor 9 signaling pathway; phagosome-lysosome fusion; regulation of immune system process
Cellular component: Golgi apparatus; late endosome; lysosome; phagocytic vesicle; trans-Golgi network; late endosome membrane; phagocytic vesicle membrane
Homologues: Orthologues: chimpanzee RAB7B (100% identical), macaque RAB7B (100% identical), pig RAB7B (91% identical), mouse Rab7b (88% identical), guinea pig RAB7B (85% identical), dog RAB7B (84% identical), rat Rab7b (82% identical), tropical clawed frog rab7b (58% identical). Paralogues in human: RAB7A (49% identical), RAB9A (40% identical), RAB9B (40% identical), RAB13 (35% identical), RAB1A (35% identical), RAB2B (35% identical), RAB4A (35% identical), RAB6A (35% identical), RAB1B (35% identical), RAB27A (35% identical), RAB35 (35% identical), RAB3B (35% identical), and 56 more.
Diseases named in the same sentence as RAB7B in open-access papers:
RAB7B is named in the same sentence as 20 diseases in open-access papers, as found by Europe PMC text mining. Sharing a sentence is not in itself a finding about the gene and the disease. The quoted sentences say what the papers report.
melanoma (2 papers, 2024). A malignant, usually aggressive tumor composed of atypical, neoplastic melanocytes. "Malme-3M, a RAB7B+ melanoma cell line, was engineered to express HLA-A*11:01+ (Malme-3MA*11:01) and tested as a target for endogenous RAB7B12–21 presentation." (PMID 39287991, 2024).
acute promyelocytic leukemia (1 paper, 2019). An aggressive form of acute myeloid leukemia (AML), characterized by arrest of leukocyte differentiation at the promyelocyte stage, due to a specific chromosomal translocation t(15;17) in myeloid cells. "A previous study reported that Rab7b played an important role in monocytic differentiation of human acute promyelocytic leukemia cells." (PMID 29769411, 2019).
allergic reaction (1 paper, 2015). "In the earlier studies, the exogenous protein of GFP and Cry1Ab/Ac could be digested without producing an allergic reaction and the TLR4 protein could be transferred to the endosome through the pathway Triad3A, Rab7b, and degenerated in the cytolysosome." (PMID 25874566, 2015).
amyotrophic lateral sclerosis (1 paper, 2021). Amyotrophic lateral sclerosis (ALS) is a neurodegenerative disease characterized by progressive muscular paralysis reflecting degeneration of motor neurons in the primary motor cortex, corticospinal tracts, brainstem and spinal cord. "RNA sequence analysis also showed that Rab7b expression was the elevated gene in mice with LRRC4 deletion involving amyotrophic lateral sclerosis." (PMID 33932995, 2021).
breast carcinoma (1 paper, 2019). "This suggested that Rab7b might participate in breast cancer development." (PMID 29769411, 2019).
cerebral infarction (1 paper, 2021). An ischemic condition of the brain, producing a persistent focal neurological deficit in the area of distribution of the cerebral arteries. "Rab7b is reportedly up-regulated in the transient middle cerebral artery occlusion (tMCAO) model, while overexpression of Rab7b in the brain can reduce cerebral infarction of tMCAO and improve neurological functions." (PMID 33932995, 2021).
Cerebral ischemia (1 paper, 2020). Restriction of arterial blood supply to the brain associated with insufficient oxygenation to support the metabolic requirements of the tissue. "Rab7b, a lysosome-associated small Rab GTPase, regulates autophagy during cerebral ischemia and confers neuroprotection against ischemic brain damage." (PMID 32089771, 2020).
Cirrhosis (1 paper, 2025). A chronic disorder of the liver in which liver tissue becomes scarred and is partially replaced by regenerative nodules and fibrotic tissue resulting in loss of liver function. "Collectively,our findings identify RAB7B as a mitophagy-related hub gene drivingliver cirrhosis progression and provide novel insights into its therapeuticpotential." (PMID 41427234, 2025). "RAB7B showed notablebinding interactions with the candidate compounds identified for treatingliver cirrhosis." (PMID 41427234, 2025). "Among them, RAB7B demonstrated stronger expression enrichmentin cirrhosis and stronger correlation with COL1α1 expression,thus prioritized for downstream validation." (PMID 41427234, 2025). "To validate the expression of RAB7B inliver cirrhosis, we quantified mRNA levels in liver specimens fromCCl4-induced cirrhotic mice." (PMID 41427234, 2025). "Surprisingly, no previous studies have specificallyaddressed the effects of RAB7B on cirrhosis or its specific role inHSCs." (PMID 41427234, 2025).
COVID-19 (1 paper, 2022). A disease caused by infection with severe acute respiratory syndrome coronavirus 2. "Using WES data, we focused on nine genes that have been reported to be involved in the SARS-CoV-2 entry pathway (ACE2, RAB7B, ADAM17, TMPRSS2), host immune response (IFNAR2, TYK2), and/or were previously shown to be associated with COVID-19 outcomes (DPP9, LZTFL1, SLC6A20)." (PMID 36292769, 2022).
hemolytic-uremic syndrome (1 paper, 2025). Acute kidney injury associated with microangiopathic hemolytic anemia and thrombocytopenia. "A number of articles demonstrate the role of Rab7b in hemolytic uremic syndrome and Pelizaeus–Merzbacher disease, suggesting the absence of Rab7b is beneficial in disease recovery." (PMID 40141252, 2025).
liver cirrhosis (1 paper, 2025). "These findingscollectively demonstrate that RAB7B expression was upregulated incirrhotic livers, providing strong evidence of a substantial associationwith liver cirrhosis." (PMID 41427234, 2025). "Dysregulationof RAB7B may impair mitochondrial clearance, promote mitochondrialaccumulation, and thereby contribute to the progression of liver cirrhosis." (PMID 41427234, 2025). "According to the bioinformatic analyses above, RAB7B could have arole in the process of liver cirrhosis." (PMID 41427234, 2025).
Stroke (1 paper, 2021). Sudden impairment of blood flow to a part of the brain due to occlusion or rupture of an artery to the brain. "In addition, studies on the cerebral ischemic stroke in the rat revealed an increased expression of Rab7b in the brain after the stroke." (PMID 33057840, 2021). "In turn, overexpression of Rab7b in rat brain reduced the TLR4 and NF-κB levels following the stroke and also reduced the production of pro-inflammatory cytokines in both signaling cascades of the receptor." (PMID 33057840, 2021).
thyroid (1 paper, 2016). "Two genes SLCA2A3, that are important for glucose transport, and RAB7B, a small GTPase that regulates transport between the different compartments of the endomembrane system in eukaryotic cells, have been found to be up-regulated in normal tissues from neoplastic thyroid patients." (PMID 27105534, 2016).
cancer (4 papers, 2017 to 2024). A tumor composed of atypical neoplastic, often pleomorphic cells that invade other tissues. "DCs isolated from healthy donors were successfully depleted for Rab7b, loaded with a specific cancer peptide (a TGFBR2 frameshift mutation-derived epitope), and further incubated with autologous T cells transfected with the validated cognate T cell receptor (TCR), Radium-1." (PMID 34494097, 2021). "Compared to Rab7a expression of Rab7b was minimal in all tested cancer lines." (PMID 39562548, 2024). "We identified cancer cell lines as expressing high levels of HTR1E and RAB7B by transcriptomics, respectively, using the 22Q4 database of the Cancer Dependency Map." (PMID 39287991, 2024).
infection (4 papers, 2013 to 2021). The state of being infected such as from the introduction of a foreign agent such as serum, vaccine, antigenic substance or organism. "During the course of infection by FMDV, VP3 interacts with Rab7b and TLR4 and subsequently attenuates the expression of Rab7b, which results in the upregulation of TLR4 expression." (PMID 34524915, 2021). "On the other hand, infection with MHV-S2′FCS was significantly diminished by downregulation of the early endosomal proteins RAB5B and RAB5C, but not of the late endosomal proteins RAB7A and RAB7B or the HOPS complex components VPS11 and VPS41 (blue bars)." (PMID 25375324, 2014).
tumor (2 papers, 2020 to 2025). "Upregulation of Tgm2 and Rab7b promotes tumor cell autophagy." (PMID 39796281, 2025).
RAB7B also shares sentences with these, for which no sentence is quoted: atherosclerosis (1 paper); liver cancer (1); liver fibrosis (1); neurological disease (1).